KIT (KIT proto-oncogene, receptor tyrosine kinase)
Diseases named in the same sentence as KIT in open-access papers (continued):
Sharing a sentence is not in itself a finding about the gene and the disease.
cutaneous melanoma (continued). "Taking into account results from cutaneous melanoma studies, the minority of MMHN patients with driver mutations of oncogenes could benefit from KIT and BRAF inhibitors." (PMID 27737700, 2016). "In contrast to metastatic melanoma from primary cutaneous melanoma, where the c-KIT expression is decreased, we could observe c-KIT expression in 9 out of 9 metastases of primary mucosal melanoma." (PMID 19018266, 2008). "Thus, c-KIT protein expression appears to be in a similar range in mucosal melanomas and cutaneous melanomas." (PMID 19018266, 2008). "In addition, cutaneous melanomas have been reported to express c-KIT by immunohistochemistry in 22.8% up to 84% of the cases." (PMID 19018266, 2008). "Finally, c-KIT missense mutations have been reported in 21% of the mucosal, 11% of the acral, and 17% of chronic sun-damaged cutaneous melanomas, while being absent however in non-sun-damaged cutaneous melanomas." (PMID 25695059, 2015). "The failure to detect KIT on skin melanomas may have several explanations." (PMID 24489649, 2014). "In cutaneous melanoma, the presence of SCF results in decreased expression of KIT and an increased density of methylation of the KIT promoter." (PMID 41160271, 2025). "Recently, targeted therapies, including inhibitors of c-KIT, NRAS/MEK or BRAF, and immunotherapies, including anti-CTLA-4 and anti-PD-1/PD-L1 antibodies, have revolutionized the treatment of cutaneous melanoma." (PMID 38326751, 2024). "Here, we used the TWM term for cutaneous melanomas where all the major oncogenic drivers are wild type: BRAF, RAS and KIT." (PMID 36980598, 2023). "Activating oncogenic mutations of BRAF have been described in many malignancies, including cutaneous melanoma (67%), colorectal carcinoma (12%), non-small cell lung carcinoma (NSCLC; 3%), and KIT wild-type GIST (13%)." (PMID 23470635, 2013). "A candidate gene approach with 20 cutaneous melanomas found no variant in BRAF, NRAS, PTEN, KIT, GNAQ, and CDK4." (PMID 31262050, 2019). "In contrast to BRAF driver mutations, KIT driver mutations are present to a higher extent in acral and mucosal melanomas (10.8% and 11.5% respectively) compared to cutaneous melanomas (9.7% in CSD and 5.1% in non-CSD cutaneous melanoma)." (PMID 36276131, 2022). "The genetic abnormalities commonly associated with these two subtypes of cutaneous melanoma are neurofibromin 1 (NF1), NRAS, BRAF non-V600E mutations, or KIT in CSID, while non-CSID is associated with BRAF V600E mutations, suggesting that the non-CSID might originate from nevi." (PMID 33256089, 2020). "We analyzed data from the skin cutaneous melanoma cohort and could identify significant negative correlation between the NRF2 target malic enzyme 1 (ME1) and KIT as well as ABCB5." (PMID 34951143, 2022).
mesenchymal tumors (99 papers, 2006 to 2026). "The discovery of c-KIT (CD117) and its overexpression in GISTs in the late 1990s revolutionized the diagnostic landscape of mesenchymal tumors of the gastrointestinal tract." (PMID 41209937, 2025). "In stark contrast, GIST, the most common mesenchymal tumor of the gastrointestinal tract, arises from Cajal interstitial cells and characteristically harbors KIT or PDGFRA mutations." (PMID 41488102, 2025). "GISTs are the most common mesenchymal tumors of the gastrointestinal tract, with a distinctive molecular pathogenesis, primarily driven by mutations in the KIT or PDGFRA genes." (PMID 39559661, 2024). "GISTs are mesenchymal tumors that display constitutive activation of KIT or PDGFRA through gene mutations, which can predict the response to imatinib-based therapy." (PMID 37907993, 2023). "GIST is a mesenchymal neoplasm derived from a precursor cell that differentiates into smooth muscle interstitial cells of Cajal in the gastrointestinal tract by c-KIT mutation or overexpression." (PMID 31410732, 2019). "GISTs, mostly caused by mutations in the PDGFRA and KIT genes, are the most common mesenchymal tumor in the gastrointestinal tract." (PMID 30653164, 2019). "GISTs are the most common mesenchymal tumor in the gastrointestinal tract, the most common of which are KIT or PDGFRα activation mutations." (PMID 27845908, 2017). "GIST are defined as mesenchymal neoplasm expressing KIT protein, driven by KIT or PDGFRα (platelet derived growth factor alpha) mutations." (PMID 17306018, 2007). "GISTs are the most common mesenchymal tumors of the gastrointestinal tract, typically arising in the stomach and small intestine, and are characterized by activating mutations in KIT or PDGFRA, which play a central role in tumorigenesis and therapeutic response." (PMID 40703587, 2025). "In GIST, TFs such as HAND and the core TF network constitutes a large positive feedback system for KIT mutant gene expression, and this positive feedback promotes the development of mesenchymal tumors." (PMID 38414063, 2024). "The protein c-KIT plays a crucial role in diagnosing GISTs and differentiating them from other mesenchymal tumors in the gastrointestinal tract." (PMID 39449907, 2024). "Mesenchymal neoplasms that arise in the GI tract are known as GISTs, and they are usually KIT-positive." (PMID 39011216, 2024). "In the general population, GISTs are the most common gastrointestinal mesenchymal tumors and typically show positive staining for KIT and DOG1 immunohistochemically." (PMID 37789344, 2023). "GISTs, the most common soft tissue sarcomas of the GI tract, most commonly contain KIT- or PDGFRA-activating mutations and are derived from mesenchymal neoplasms in the GI tract." (PMID 35672812, 2022). "DOG1.1 is a recently described mouse monoclonal antibody reported to have superior sensitivity and specificity compared with KIT (CD117 Small subset of mesenchymal tumors like leiomyosarcoma and synovial sarcoma also show DOG1 positivity." (PMID 35199796, 2021). "To date, GIST is defined as a specific, KIT-expressing and KIT-signaling driven mesenchymal tumor of the gastrointestinal tract." (PMID 31220684, 2019). "Gastrointestinal stromal tumors (GISTs) are the most common mesenchymal tumor in the gastrointestinal tract, the most common of which are KIT or PDGFRα (platelet-derived growth factor receptor alpha) activation mutations." (PMID 27845908, 2017). "GIST is defined as a mesenchymal tumor that immunohistochemically exhibits KIT (CD117) and/or DOG1 positivity." (PMID 28111536, 2017). "GISTs are defined as pleomorphic mesenchymal tumors of the GI tract composed of spindle cells, epithelioid cells, or a combination of both, that express the c-KIT protein and, in most cases, CD34, as demonstrated by immunohistochemical staining." (PMID 25037940, 2014). "KIT has been demonstrated as a very specific and sensitive marker to mesenchymal tumors in the GI tract and around 95% of GISTs express KIT." (PMID 24027646, 2013).
mesenchymal tumors (continued). "KIT and PDGFRA mutations drive mesenchymal tumors, including GISTs (gastrointestinal tract sarcomas)." (PMID 23420084, 2013). "GISTs are defined as pleomorphic mesenchymal tumors of the gastrointestinal tract composed of spindle cells, epithelioid cells, or a combination of both that express the KIT protein (CD 117) and in most cases CD34 on immunohistochemistry." (PMID 23243532, 2012). "Among mesenchymal tumors on the digestive tract wall, KIT-expressing tumors are regarded as GIST, which are considered to be derived from the interstitial cells of Cajal cells." (PMID 18664259, 2008). "GISTs are mesenchymal tumors, the majority of which is KIT (CD117)-positive, typically arising in association with the muscularis propria of the gastrointestinal tract wall." (PMID 17565683, 2007). "The benefit of evaluating metabolic response using [18F]FDG PET/CT is well demonstrated in KIT- or PDGFRA- mutated GIST tumours following treatment with the tyrosine kinase inhibitor; imatinib, as mesenchymal tumours such as GIST rarely demonstrate a reduction in size despite therapeutic response." (PMID 33443647, 2021). "Gastrointestinal stromal tumours (GIST) are the most common mesenchymal tumours of the gastrointestinal tract, and the majority of adult onset GIST, so-called ‘tyrosine kinase mutant’ GIST (TK-mutant GIST), are driven by activating somatic mutations in the KIT or PDGFRA genes." (PMID 33443647, 2021). "Recently, the expression of HER2, EGFR1, VEGFR-2, PDGFR-β, c-KIT, and ERK1/ERK2 has been investigated in various canine tumors, with mesenchymal tumors showing the lowest expression levels and carcinomas showing the highest expression levels." (PMID 40417261, 2025). "A recent study found that reconstitution/recombination of MITF restored KIT expression levels in SH3BP2-silenced cells and restored cell viability in mesenchymal tumors, while also reducing MITF and ETV1 expressions." (PMID 38414063, 2024). "Immunohistochemical analysis typically reveals strong positivity for KIT (CD117) and CD34, aiding in the diagnosis of gastric GIST and distinguishing them from other mesenchymal neoplasms." (PMID 39064037, 2024). "These cells are known to express the KIT gene (detected as the cluster of differentiation [CD]117 antigen), which is important for distinguishing GIST from other mesenchymal neoplasms." (PMID 24932260, 2014). "Moreover, 99.5% of the tumors in the KIT-high subgroup were classified as CMS4, further confirming the high expression of KIT in mesenchymal tumors." (PMID 35842424, 2022). "CD117 (c-KIT) provides a useful membranous and some cytoplasmic staining, unlike other mesenchymal tumors, which stain only cytoplasmic pattern with coarse granules." (PMID 33042684, 2020). "This is largely due to the fact that greater than 85% of GIST test positive for v-kit Hardy-Zuckerman 4 feline sarcoma viral oncogene homolog (KIT), in contrast to the negative result generated by most other mesenchymal tumors." (PMID 24199171, 2013). "Immunohistochemistry typically demonstrates strong CD34 positivity and negative staining for CD117 (c-KIT), DOG1, S-100, and desmin, distinguishing them from other GI mesenchymal tumors." (PMID 41562800, 2025).
chronic myeloid leukemia (89 papers, 2004 to 2026). "A previous study has shown that Dasatinib not only inhibits the BCR-ABL kinase of chronic myeloid leukemia, but also inhibits KIT kinase, including KIT mutation encoded KIT kinase." (PMID 34659343, 2021). "An important example is imatinib, a kinase inhibitor originally approved for the treatment of patients with BCR-ABL-positive chronic myeloid leukemia, which is also a very effective inhibitor of KIT and thus showed increased efficacy in KIT-mutated GIST." (PMID 28955656, 2017). "Few notable successes in this field include the identification of trastuzumab-responsive breast cancers by testing for Her2-neu, BCR/ABl translocation in chronic myeloid leukemia, and KIT mutations in imatinib-responsive GIST." (PMID 27509178, 2016). "The KIT D816V oncogenic mutation triggers resistance to the RTK inhibitor Imatinib used as first line treatment against chronic myeloid leukemia and gastrointestinal tumors." (PMID 24828813, 2014). "Imatinib is the first receptor tyrosine kinase (RTK) inhibitor with activity against ABL, BCR-ABL, PDGFR, and c-KIT, and is the standard of care in chronic myelogenous leukemia (CML), GIST, DFSP, and various other cancers." (PMID 40558511, 2025). "For instance, mice deficient in either KIT or SCF lack tissue mast cells, and imatinib, a KIT kinase inhibitor, reduces mast cell number after long-term dosing in patients with chronic myelogenous leukemia." (PMID 38764489, 2024). "Dasatinib is one of the second-generation tyrosine kinase inhibitors used to treat chronic myeloid leukemia and has a broad target spectrum, including KIT, PDGFR, and SRC family kinases." (PMID 38903922, 2024). "Major advances were made in the treatment of chronic myeloid leukaemias and gastrointestinal tumours by using drugs that directly inhibit the pathways deregulated by the BCL2-ABL fusion gene and c-KIT mutations." (PMID 17406368, 2007). "We selected imatinib for our analysis as it shows promising but limited efficacy in clinical trials for NB and AML (NCT00030667 and NCT01126814) and is successfully used for chronic myeloid leukemia treatment, and both types of cancer express KIT, which is one of the main imatinib target." (PMID 34944663, 2021). "Imatinib has indeed changed the fate of patients with GIST and Philadelphia chromosome-positive chronic myeloid leukemia by targeting the oncogenic drivers of these diseases—BCR–ABL1 and KIT and/or PDGFRA—mutations that promote the function of tyrosine kinase activities." (PMID 33552970, 2020). "Therefore, imatinib was approved for the treatment of chronic myelogenous leukemia (CML) caused by BCR-ABL over expression, c-KIT-positive metastatic tumor and gastrointestinal stromal tumor." (PMID 25629045, 2015). "Imatinib (STI571), a receptor tyrosine kinase inhibitor with effects on the bcr-abl tyrosine kinase, platelet-derived growth factor receptor (PDGFR) and c-KIT is now standard treatment in patients with chronic myeloid leukaemia and the rare gastrointestinal stromal tumours (GIST)." (PMID 15305185, 2004). "First-generation TKIs such as imatinib, which inhibit KIT, PDGFR, and BCR-ABL, revolutionized first-line therapy for GIST and chronic myeloid leukemia (CML)." (PMID 41517566, 2026). "Dasatinib exhibits a favorable therapeutic profile in the treatment of chronic myeloid leukemia (CML) through the inhibition of BCR-ABL kinases, including c-KIT, EPH receptor kinase, PDGFRβ, and SRC family kinases, among other oncogenic kinases." (PMID 39836268, 2025). "These drugs selectively inhibit aberrant kinases like BCR-ABL, c-KIT, and PDGFR, which are involved in the pathogenesis of cancers such as chronic myeloid leukemia (CML) and gastrointestinal stromal tumors (GISTs)." (PMID 40649226, 2025). "Imatinib is a selective multi-kinase inhibitor that targets BCR-ABL, KIT and PDGFR and is an FDA-approved drug to treat chronic myeloid leukemia." (PMID 38239643, 2023).
chronic myeloid leukemia (continued). "Differential diagnosis of MML includes wild-type KIT MCL, SM-AML, chronic eosinophilic leukemia (with increased atypical mast cells), and chronic myeloid leukemia (with increased metachromatic basophils)." (PMID 35884535, 2022). "Imatinib is approved by the US FDA for the treatment of chronic myeloid leukemia (CML) and targets the phosphorylation of RTKs including PDGFR-b and v-Kit Hardy–Zuckerman 4 feline sarcoma viral oncogene homolog (c-KIT)." (PMID 34440080, 2021). "Imatinib is one outstanding example which is used in the treatment of chronic myelogenous leukemia (CML) with a significant therapeutic effect by specifically inhibiting tyrosine kinases BCR-ABL, c-KIT, and PDGFRA." (PMID 33763427, 2021). "While Imatinib is a well-known inhibitor for various tyrosine kinases such as ABL1, ABL2, KIT, and PDGFR and has been used to treat chronic myelogenous leukemia and solid tumors, little is known about how it can affect intracellular bacterial infections." (PMID 34782676, 2021). "Nilotinib can overcome imatinib-resistant chronic myeloid leukemia (CML) and also selectively inhibits KIT and PDGFR." (PMID 25221952, 2014). "Imatinib mesylate (Gleevec, STI571), an inhibitor of ABL, PDGFRα, and KIT tyrosine kinases, is successfully applied to the treatment of BCR-ABL-positive chronic myelogenous leukemia (CML)." (PMID 25431951, 2014). "Nilotinib is designed based on the structure of IM and shows higher affinity to the ATP-binding site of ABL kinase to overcome IM-resistant chronic myeloid leukemia (CML) and also selectively inhibits KIT and PDGFR." (PMID 23840364, 2013). "The success of KIT-targeting imatinib mesylate in the treatment of GIST and chronic myelogenous leukemia may be relevant for DG treatment." (PMID 33435376, 2021). "Dasatinib is a Src, BCR-ABL, c-KIT, PDGFR-α and PDGFR-β, and ephrin receptor kinase blockers accepted by the Food and Drug Administration (FDA) for treating cases of Philadelphia chromosome positive leukemias (chronic myeloid leukemia; CML)." (PMID 34204015, 2021). "Imatinib, the first approved drug in this category, is an adenosine triphosphate, competitive inhibitor of KIT, PDGFRA, BCR-ABL, and ABL tyrosine kinases, which was already used in the treatment of patients with chronic myeloid leukemia (CML) who bear the BCR-ABL fusion gene." (PMID 26075122, 2015). "For example, dasatinib, an oral BCR-ABL TKI, is approved for chronic myeloid leukemia, Philadelphia-positive leukemia, chronic myeloproliferative disorders with PDGFRβ rearrangements, some mast cell leukemias (MCL) with noncanonical KIT mutations, and KIT-positive AML." (PMID 41199910, 2025).